PSMD14 (proteasome 26S subunit, non-ATPase 14)
Description:
Component of the 26S proteasome, a multiprotein complex involved in the ATP-dependent degradation of ubiquitinated proteins. This complex plays a key role in the maintenance of protein homeostasis by removing misfolded or damaged proteins, which could impair cellular functions, and by removing proteins whose functions are no longer required. Therefore, the proteasome participates in numerous cellular processes, including cell cycle progression, apoptosis, or DNA damage repair. The PSMD14 subunit is a metalloprotease that specifically cleaves 'Lys-63'-linked polyubiquitin chains within the complex. Plays a role in response to double-strand breaks (DSBs): acts as a regulator of non-homologous end joining (NHEJ) by cleaving 'Lys-63'-linked polyubiquitin, thereby promoting retention of JMJD2A/KDM4A on chromatin and restricting TP53BP1 accumulation. Also involved in homologous recombination repair by promoting RAD51 loading. Regulates macroautophagy by ensuring Golgi-to-ER retrograde transport through its deubiquitinating activity on K63-linked ubiquitin chains. This activity prevents the retention of essential autophagy proteins at the Golgi, enabling their trafficking to autophagosome formation sites and supporting Golgi-ER membrane recycling critical for effective autophagy.
Synonyms: POH1; pad1; Rpn11
Tractability: Small molecule: an approved drug acts on it; a structure with a bound ligand is known; a high-quality ligand is known; it belongs to a druggable protein family. Antibody: its Gene Ontology location is reachable by antibodies, with high confidence. PROTAC: ubiquitination databases record sites on it; its protein half-life has been measured; a small molecule that binds it is known.
Target class: Metallo protease; Protease; Enzyme; Metallo protease M67A subfamily; Metallo protease M67 family; Metallo protease MP clan
Chemical probes: Capzimin
Gene: Protein-coding gene on chromosome 2 (161,308,414 to 161,411,720, forward strand). Ensembl gene ENSG00000115233.
Subcellular location (Human Protein Atlas): Nucleoplasm
Pathways (Reactome):
Immune System: AMPK-induced ERAD and lysosome mediated degradation of PD-L1(CD274); Activation of NF-kappaB in B cells; Antigen processing: Ubiquitination & Proteasome degradation; CLEC7A (Dectin-1) signaling; Cross-presentation of soluble exogenous antigens (endosomes); Dectin-1 mediated noncanonical NF-kB signaling; Downstream TCR signaling; ER-Phagosome pathway; FCERI mediated NF-kB activation; GSK3B-mediated proteasomal degradation of PD-L1(CD274); Interleukin-1 signaling; NIK-->noncanonical NF-kB signaling; Neutrophil degranulation; SPOP-mediated proteasomal degradation of PD-L1(CD274); TNFR2 non-canonical NF-kB pathway
Cell Cycle: APC/C:Cdc20 mediated degradation of Securin; APC/C:Cdh1 mediated degradation of Cdc20 and other APC/C:Cdh1 targeted proteins in late mitosis/early G1; Autodegradation of Cdh1 by Cdh1:APC/C; Autodegradation of the E3 ubiquitin ligase COP1; Cdc20:Phospho-APC/C mediated degradation of Cyclin A; FBXL7 down-regulates AURKA during mitotic entry and in early mitosis; G2/M Checkpoints; SCF(Skp2)-mediated degradation of p27/p21; SCF-beta-TrCP mediated degradation of Emi1; Separation of Sister Chromatids; The role of GTSE1 in G2/M progression after G2 checkpoint; Ubiquitin-Mediated Degradation of Phosphorylated Cdc25A; Ubiquitin-dependent degradation of Cyclin D
Signal Transduction: Asymmetric localization of PCP proteins; Degradation of AXIN; Degradation of DVL; Degradation of GLI1 by the proteasome; Degradation of GLI2 by the proteasome; Degradation of beta-catenin by the destruction complex; GLI3 is processed to GLI3R by the proteasome; Hedgehog 'on' state; Hedgehog ligand biogenesis; MAPK6/MAPK4 signaling; Negative regulation of NOTCH4 signaling; Regulation of PTEN stability and activity
and 29 more pathways
Gene Ontology:
Molecular function: cysteine-type deubiquitinase activity; endopeptidase activator activity; K63-linked deubiquitinase activity; metal-dependent deubiquitinase activity; proteasome binding; protein binding; metallopeptidase activity; peptidase activity
Biological process: double-strand break repair via homologous recombination; double-strand break repair via nonhomologous end joining; protein K63-linked deubiquitination; regulation of macroautophagy; regulation of proteasomal protein catabolic process; retrograde vesicle-mediated transport, Golgi to endoplasmic reticulum; cellular response to type I interferon; proteasomal protein catabolic process; proteasome-mediated ubiquitin-dependent protein catabolic process; protein deubiquitination; response to oxidative stress; ubiquitin-dependent protein catabolic process; response to ethanol
Cellular component: nucleoplasm; nucleus; proteasome complex; proteasome regulatory particle, lid subcomplex; cytosol; extracellular region; ficolin-1-rich granule lumen; proteasome accessory complex; secretory granule lumen; synaptic vesicle; cytosolic proteasome complex
Genetic constraint (gnomAD): Loss-of-function variants: 3 observed, 20.78 expected, observed/expected ratio (o/e) 0.14, 90% interval 0.065 to 0.37. The upper end of that interval is the gene's LOEUF score, 0.37, which puts it in group 1 of 6, group 1 being the genes least tolerant of losing a copy. Missense variants: 66 observed, 202.84 expected, observed/expected ratio (o/e) 0.33, 90% interval 0.27 to 0.4. Synonymous variants: 65 observed, 66.75 expected, observed/expected ratio (o/e) 0.97, 90% interval 0.8 to 1.2.
Homologues: Orthologues: chimpanzee PSMD14 (100% identical), dog PSMD14 (100% identical), guinea pig PSMD14 (100% identical), macaque PSMD14 (100% identical), mouse Psmd14 (100% identical), rat Psmd14 (100% identical), tropical clawed frog psmd14 (99% identical), zebrafish psmd14 (98% identical), pig PSMD14 (96% identical), Drosophila melanogaster Rpn11 (88% identical), rabbit PSMD14 (85% identical), Caenorhabditis elegans rpn-11 (75% identical). Paralogues in human: COPS5 (32% identical), BRCC3 (22% identical), EIF3H (20% identical).
Diseases named in the same sentence as PSMD14 in open-access papers:
PSMD14 is named in the same sentence as 70 diseases in open-access papers, as found by Europe PMC text mining. Sharing a sentence is not in itself a finding about the gene and the disease. The quoted sentences say what the papers report.
breast carcinoma (18 papers, 2014 to 2026). "For instance, in breast cancer, PSMD14 removes K63-linked ubiquitin chains from FOXM1 to activate the PI3K/AKT/mTOR pathway, thereby facilitating malignant progression." (PMID 41488674, 2025). "We found that PSMD14 is correlated with the gene signature of ERα signaling and associated with poor survival in luminal type breast cancer." (PMID 38017133, 2024). "We discovered that PSMD14 facilitates breast cancer progression by modulating ERα K48-linked deubiquitinating, thereby enhancing ERα signaling activity." (PMID 38017133, 2024). "Accumulating evidence has linked PSMD14 to the pathogenesis of multiple human cancers—such as breast cancer, hepatocellular carcinoma, bladder cancer, glioblastoma, and osteosarcoma —where it facilitates tumor progression primarily by stabilizing key oncogenic substrates through deubiquitination." (PMID 41488674, 2025). "Similarly, high expression of PSMD14 is associated with a worse prognosis in multiple myeloma, esophageal, ovarian, breast cancer and osteosarcoma." (PMID 35750900, 2023). "CONCLUSION: This study identifies PSMD14 as a critical regulator of immune responses in breast cancer." (PMID 41981629, 2026). "METHODS: PSMD14 expression and its prognostic significance in breast cancer were analyzed using public databases and clinical samples." (PMID 41981629, 2026). "PSMD14 has been demonstrated to act as an oncogene in a wide range of human cancers, e.g., ovarian cancer, liver cancer, gastric cancer, breast cancer, esophageal squamous cell carcinoma, and lung adenocarcinoma." (PMID 40182048, 2025). "Studies demonstrated that PSMD14 promoted the development of a variety of cancers, including neck squamous cell carcinoma, breast cancer, and myeloma." (PMID 40066751, 2025). "A study revealed that estrogen receptor alpha bound to the PSMD14 promoter region and promoted the transcription of this gene, which promoted breast cancer progression." (PMID 40066751, 2025). "This novel positive feedback loop reveals a non-genomic regulation mechanism for ERα signaling and highlights PSMD14 as a potential therapeutic target for breast cancer treatments." (PMID 38017133, 2024). "In human malignancies, PSMD14 was over-expressed in liver cancer, esophageal carcinoma and breast cancer, which expression also related to poor overall survival." (PMID 38017133, 2024). "We illustrated that the expression of PSMD14 was increased in breast cancer and related to poor survival only in luminal type breast cancer patients." (PMID 38017133, 2024). "The subgroup analysis showed that PSMD14 was increased in all subtype of breast cancer samples and all stages of breast cancers." (PMID 38017133, 2024). "We further investigated PSMD14 expression in human breast cancer, which showed that PSMD14 was elevated in breast malignancies from TCGA database." (PMID 38017133, 2024). "The CCK8 assay further indicated that PSMD14 depletion restored the inhibitory effect of tamoxifen in breast cancer cells." (PMID 38017133, 2024). "PSMD14 interacted with ERα protein, inhibited ERα poly-ubiquitination and proteasome-dependent degradation in breast cancer cells." (PMID 38017133, 2024). "Through deubiquitinases siRNA library screening, we discover PSMD14 as a critical deubiquitinase for ERα signaling and breast cancer progression." (PMID 38017133, 2024). "We further examined the protein level of PSMD14 in breast cancer patient samples through immunohistochemistry (IHC), while PSMD14 expression was significantly increased in breast cancers (3/25 vs 23/25; P < 0.001)." (PMID 38017133, 2024). "In conclusion, we proved PSMD14 as an oncogene for breast cancer both in clinical samples and experimental studies." (PMID 38017133, 2024). "Although we uncover the regulatory feedback loop between ERα and PSMD14 in luminal type breast cancer, there are several limitations of our study." (PMID 38017133, 2024).
breast carcinoma (continued). "Utilizing this model, we evaluated the effect of PSMD14 on the breast cancer phenotype and ERα signaling in an endocrine resistant background." (PMID 38017133, 2024). "We found that the expression of MDC1, PSMB1 and PSMD14 were concurrently upregulated in breast cancer samples, suggesting the potential of the prognostic model." (PMID 37350936, 2023). "Subsequently, we explored the protein levels of MDC1, PARP3, PSMB1, PSMB9, PSMD2, PSMD7, and PSMD14 in normal breast tissues and breast cancer tissues." (PMID 37350936, 2023). "Consistent with the Immunohistochemistry (IHC) results, the expression of MDC1, PSMB1, PSMD2, PSMD7 and PSMD14 were significant augmented in breast cancer patients (P < 0.05)." (PMID 37350936, 2023). "The levels of PSMD1, PSMD2, PSMD3, PSMD7, PSMD10, PSMD12, and PSMD14 are high in breast cancer tissue compared to normal tissues." (PMID 36934426, 2023). "Our results suggest that focusing on PARP3, PSMB1, PSMD7, and PSMD14 and their roles in immunotherapy is a reasonable strategy for breast cancer treatment." (PMID 37350936, 2023). "We found that both proteasome inhibition and intracellular Ca2+ imbalance critically contribute to the paraptosis induced by PSMD14 inhibition in breast cancer cells." (PMID 35269789, 2022). "Recently, PSMD14 has been shown to play role in hepatocellular carcinoma, breast cancer, and prostate cancer." (PMID 34383385, 2022). "We herein show for the first time that pharmacological or genetic inhibition of PSMD14 in several breast cancer cells induces paraptosis as a major cell death mode." (PMID 35269789, 2022). "RESULTS: PSMD14 was highly expressed in breast cancer and correlated with poor patient prognosis." (PMID 41981629, 2026). "PSMD14 modulates the progression of breast cancer through ERα signaling." (PMID 40182048, 2025). "PSMD14 could facilitate breast cancer progression through ERα signaling in vitro and in vivo, while pharmaceutical inhibition of PSMD14 via Thiolutin could block the tumorigenesis in breast cancer." (PMID 38017133, 2024). "We further analyzed the prognosis of PSMD14 expression in PR+ breast cancer patients." (PMID 38017133, 2024). "Furthermore, the depletion of ERα in breast cancer cells resulted in a decrease in PSMD14 mRNA levels." (PMID 38017133, 2024). "Additionally, we analyzed the expression of PSMD14 in breast cancer samples, using IHC, and its correlation with molecular/clinical characteristics, such as ERα, PR, and HER2 status." (PMID 38017133, 2024). "In our study, our DUB screening data revealed PSMD14 was a critical factor, which could be a useful drug target for breast cancer." (PMID 38017133, 2024). "The survival data showed that PSMD14 correlated with poor survival in all breast cancer patients." (PMID 38017133, 2024). "In general, we identified a novel positive feedback loop between PSMD14 and ERα signaling in breast cancer progression, while blockade of PSMD14 could be a plausible strategy for luminal breast cancer." (PMID 38017133, 2024). "We further explored the localization of PSMD14 and ERα in breast cancer cells." (PMID 38017133, 2024). "As a novel modulator for estrogen signaling, modulation of PSMD14 activity or gene expression level could be an appealing strategy to treat breast cancer." (PMID 38017133, 2024). "In addition, we investigated the roles of MDC1, PSMB1, PSMD2, PSMD7, and PSMD14 in the invasion and metastasis of breast cancer." (PMID 37350936, 2023). "We established a seven-gene prognostic model comprising MDC1, PARP3, PSMB1, PSMB9, PSMD2, PSMD7, and PSMD14 genes, which provides a basis for further exploration of a population-based prediction of prognosis and immunotherapy response in patients with breast cancer." (PMID 37350936, 2023). "Furthermore, we investigated the function of the five highly expressed genes (MDC1, PSMB1, PSMD2, PSMD7, and PSMD14) in breast cancer MDA-MB-231 cells to test the prognostic model." (PMID 37350936, 2023).
breast carcinoma (continued). "Besides, PSMD14 was also increased in ERα positive breast cancer samples." (PMID 38017133, 2024). "Interestingly, ChIP assay shows that ERα could bind to the promoter region of PSMD14 and facilitate its gene transcription, which indicates PSMD14 is both the upstream modulator and downstream target for ERα signaling in breast cancer." (PMID 38017133, 2024). "Firstly, the regulation mechanism was based on several ER+ cancer cell lines, while it is worthwhile to identify in vivo whether genetic depletion of PSMD14 in mammary gland could regulate breast epithelial cells and subsequently carcinogenic process of breast cancer in transgenic mouse models." (PMID 38017133, 2024). "PSMD14 could be a novel drug target for breast cancer treatment." (PMID 38017133, 2024). "NUDCD1, ENY2, PNO1, CCT4 and PSMD14 are considered to promote the proliferation, invasion and treatment resistance of tumor cells in a variety of cancers, including pancreatic cancer, rectal cancer, liver cancer, breast cancer, glial cancer and head and neck squamous cell carcinoma." (PMID 37827692, 2023). "Excessive expression of PSMD14 is associated with higher TNM stage in lung adenocarcinoma, increased vascular invasion in hepatocellular carcinoma, higher pathological grade in prostate cancer, and poor survival in patients with colorectal cancer or breast cancer." (PMID 34382324, 2021). "This study investigates how PSMD14 regulates PD-L1 and reshapes the TME, with the goal of clarifying its impact on immune regulation in breast cancer." (PMID 41981629, 2026). "However, the regulation of PSMD14 in estrogen signaling remains unclear in breast cancer." (PMID 38017133, 2024). "The results indicated a positive correlation between PSMD14 and several ERα target genes, including GREB1, TFF1, and MCM6, in breast cancer samples." (PMID 38017133, 2024). "The protein levels of MDC1, PSMB1, PSMB9, PSMD2, PSMD7, and PSMD14 were increased, while that of PARP3 was decreased in breast cancer tissues compared with normal tissues." (PMID 37350936, 2023). "Six paired breast cancer tissues and adjacent normal tissues to verify the protein expression level of MDC1, PSMB1 and PSMD14 via immunohistochemical staining." (PMID 37350936, 2023). "We analyzed a prognostic model based on seven DDR genes, PSMD2, PSMD7, PSMD14, PARP3, MDC1, PSMB1, and PSMB9, reflecting an enhanced level of predicting the survival and prognosis of patients with breast cancer." (PMID 37350936, 2023). "To investigate the potential of PSMD14 as a cancer target, we investigated the effects of knockdown and pharmacological inhibition of PSMD14 in MDA-MB 435S breast cancer cells." (PMID 35269789, 2022). "Recently, PSMD14 has been reported as an anti-proteasome target for tumor therapies in a number of cancer types, including HCC, breast cancer and ovarian cancer 27-29." (PMID 34234864, 2021). "Here, we show that the silencing and pharmacological blockade of PSMD14 in MDA-MB 435S breast cancer cells induce paraptosis, a non-apoptotic cell death mode characterized by extensive vacuolation derived from the endoplasmic reticulum (ER) and mitochondria." (PMID 35269789, 2022). "Collectively, our results suggest that inhibition of PSMD14 may trigger paraptosis through the simultaneous inhibition of proteasome activity and Ca2+ homeostasis in MDA-MB 435S breast cancer cells." (PMID 35269789, 2022). "Downregulation of PSMD14 expression can induce G0/G1 phase arrest, apoptosis, and can diminish proliferation and epithelial–mesenchymal transition (EMT) in lung adenocarcinoma, prostate cancer, and breast cancer cells." (PMID 34382324, 2021). "However, the oncogenic mechanism of PSMD14 in breast cancer is not totally clear." (PMID 38017133, 2024).